IL1B (interleukin 1 beta)
Diseases named in the same sentence as IL1B in open-access papers (continued):
Sharing a sentence is not in itself a finding about the gene and the disease.
diabetes (continued). "This supports that WAT NLRP3 inflammasome/IL-1β pathway is a mechanism linking hyperapoB to diabetes risk, however; it does not exclude other mechanisms." (PMID 37914804, 2023). "In a hyperglycemic environment, reactive oxygen species (ROS) activate NLRP3 inflammatory vesicles in pancreatic β-cells, promoting IL-1β secretion leading to insulin secretion dysfunction, promoting obesity and insulin resistance, and ultimately inducing type 2 diabetes mellitus raw." (PMID 37443131, 2023). "Furthermore, Baggiolini, Dewald observed enhanced TNF-α, IL-1β, and IL-8 levels in neutrophils in patients with diabetes." (PMID 37893490, 2023). "Consequently, this modulation influences the severity of various ailments such as Alzheimer’s disease, myocardial disorders, and diabetes by impacting the expression of pro-inflammatory cytokines like IL-1β, IL-6, TNF-α, and type 1 interferons." (PMID 38001481, 2023). "More specifically, PTGS2 and IL1B genes were upregulated in children with diabetes." (PMID 38096208, 2023). "Similarly, weekly intraperitoneal injections of 50 μg/mL of anti-IL-17A significantly decreased (p < 0.05) diabetes-mediated IL-1β, IL-6, TNF-α, and ZO-1 degradation in the retinas of db/db-Type II diabetic mice 2 months post-diabetes." (PMID 36674854, 2023). "However, 6 months after the induction of diabetes, the expression levels of Ccl2, Il1b, Il6, Tnf, Tgfb and Inos (Nos2) were significantly higher in the Il33−/− retina than in the WT retina." (PMID 37671525, 2023). "Similarly, during the in vitro treatment of LPS-stimulated PBMCs isolated from type 1 diabetes patients, we observed substantially increased IL-1β secretion compared to the non-diabetes population." (PMID 36918798, 2023). "Pyroptosis, a type of programmed cell death characterized by cytoplasmic destruction, membrane pore formation, DNA fragmentation, and the release of the proinflammatory cytokines IL-1β and IL-18, is involved in various acute and chronic kidney diseases, including kidney injury in diabetes mellitus." (PMID 37261217, 2023). "Notably, the OI + LPS monocytes presented attenuated IL-1β secretion compared with LPS-only-treated cells from the non-diabetes or type 1 diabetes participants." (PMID 36918798, 2023). "In addition, lower levels of inflammatory factors, including IL-1β and IL-18, were detected by ELISAs in the retinas of EC FtoΔ/Δ mice after introduction of diabetes." (PMID 37781923, 2023). "Unlike WAT IL-1β-secretion, the expression of WAT NLRP3 and to a lesser extent IL1B was positively associated with all diabetes risk factors examined with no group-differences." (PMID 37914804, 2023). "A study discovered that the induction of diabetes with STZ caused the infiltration of immune cells (macrophages and monocytes), as well as an overproduction of the pro-inflammatory cytokine interleukin-1 beta and the expression of neurotrophin receptor p75 in neurons." (PMID 37189822, 2023). "Diabetes associates with a whole-body low-grade inflammatory status characterized by elevated production of circulating cytokines such as IL-6, TNFα, IFNγ, TGFβ, MCP1, or IL-1b." (PMID 34623540, 2023). "The role of IL1B in diabetes mellitus has been investigated recently in59." (PMID 37365269, 2023). "However, associations of IL-1β, IL-10, IL-12 p70, MCP-3, and TNF-α with TIR remained significant after adjustment to BMI, as well as other possible confounders (age, sex, diabetes duration, and eGFR)." (PMID 37893217, 2023). "While IL-1β, IFNγ and TNFα have all been detected in islet infiltrates from human donors with type 1 diabetes, most of our understanding of their effects and functional pathobiology in diabetes comes from rodent model systems." (PMID 37113489, 2023). "However, to the best of our knowledge, there was no study that reported the effect of ST on the hepatic NLRP3, caspase-1, and IL-1β in diabetes rat models induced by STZ, which emphasizes the importance of this study." (PMID 38131990, 2023).
diabetes (continued). "IL1β promotes both systemic and tissue inflammation in diabetes, including β-cell apoptosis of pancreatic islets and diabetic cardiovascular complications related to increased IL1β expression in the aorta endothelium, heart and retinal vessels of diabetic rats." (PMID 36982878, 2023). "There is sufficient evidence to show that compared to patients with simple periodontitis, patients with combined diabetes and periodontitis have increased proinflammatory cytokines IL-6 and IL-1β, and there is a quantitative relationship between glycemic control and these cytokines." (PMID 37664859, 2023). "In preclinical studies, IL-1β has been identified as a key mediator of macrophage-induced insulin resistance in human adipocytes, and its high levels in VAT predispose obese rodents to the development of diabetes." (PMID 38139276, 2023). "IL-1β is a proinflammatory cytokine that not only acts as a mediator of the peripheral immune response to infections and inflammation but also plays an important role in acute and chronic autoimmune diseases, diabetes, pain, and neurological disorders." (PMID 37007766, 2023). "On the other hand, higher LPS-induced IL-1β-secretion was associated with diabetes risk factors without a group-differences." (PMID 37914804, 2023). "Diabetes is associated with changes in GSH metabolism, which may possibly contribute to an increase in TNF-α and IL-1b." (PMID 37371821, 2023). "FSH may also be associated with diabetes through inflammatory markers, such as c-reactive protein, TNF-α, and IL-1β." (PMID 36767197, 2023). "In summary, the application of cMDSCs propagated from GM-CSF, IL-6, and IL-1β cytokines can improve renal function and increase insulin secretion from pancreatic islets, thereby prolonging the diabetes-free survival of NOD–SCID mice after treatment with T cells." (PMID 37296628, 2023). "IL-1β is also involved in the pathogenesis of diabetes mellitus." (PMID 37919797, 2023). "Diabetes promotes the production of IL-1β and TNF-α by macrophages, which may contribute to the enhancement of peri-implant infection." (PMID 36875028, 2023). "In addition, studies have reported that IL-1β is inversely correlated with IL-10 in the healthy population; however, when diabetes mellitus occurs, the balance between anti-inflammatory IL-10 and proinflammatory IL-1β is broken." (PMID 36582230, 2022). "We delved deeper into the specifics of MAM protein-protein interactions and discovered key connections between many of the altered MAM proteins in diabetes with several major protein regulators of inflammation, diabetes, and/or DR, specifically IL-1β, NFκBIA, FOXO1, SYVN1, STAT4, MAF, and LGALS3." (PMID 36139394, 2022). "In an STZ-induced diabetic mouse trauma model, melatonin-pretreated exosomes derived from mesenchymal stem cells (MT-Exo) effectively inhibited the pro-inflammatory factors IL-1β and TNF-α, while the relative expression of anti-inflammatory factor IL-10 was increased." (PMID 36601058, 2022). "Many reports have shown that diabetes results in proinflammatory, phagocytic microglial activation, characterized by an ameboid shape with truncated, retracted cellular processes and microglia-derived IL-1β and NOS2 production." (PMID 36517889, 2022). "For example, autoimmunity in diabetes may release inflammatory cytokines, such as IL-1β and TNFα, which contribute to a chronic inflammatory state." (PMID 35631084, 2022). "Previous studies have shown that islet amyloid polypeptide (IAPP) is a protein formed in patients with diabetes that causes activation of the NLRP3 inflammasome, triggering a series of inflammatory responses that produce mature IL-1β, a process also known as glucose metabolism." (PMID 35647057, 2022). "However, during diabetes progression, many factors, such as amylin and IL-1β, induce upregulation of Fas, mediating β-cell apoptosis." (PMID 36672747, 2022).
diabetes (continued). "We have previously shown that renal ischemia-reperfusion triggers cardiac arrhythmia through NLRP3 inflammasome activation and IL-1β production, and in diabetes mellitus, the NLRP3 inflammasome connects metabolic dysfunction to cardiac arrhythmias through IL-1β production." (PMID 36341442, 2022). "They presented in patients with morbid obesity and type 2 diabetes mellitus with normal glucose tolerance that caspase-1 levels are normalised after weight loss, whereas IL-1β is normalised only in people without diabetes mellitus." (PMID 36231470, 2022). "Therefore, 12 weeks of Tai Chi intervention can significantly decrease the expressions of NEK7, NLRP3, ASC, Caspase-1, GSDMD, IL-1β, and IL-18, while increasing the expression of irisin in pre-diabetes." (PMID 36248820, 2022). "This eventually leads to an overproduction of IL-1β in the adipose tissue explaining a relationship between CHIP and type 2 diabetes mellitus as the IL-1β-mediated autoinflammatory process is regarded as a major factor in the loss of beta-cell mass in type 2 diabetes." (PMID 35657494, 2022). "IL-1β is essential in the development of retinopathy in diabetes." (PMID 35410316, 2022). "Similarly, the incidence of other stroke‐associated comorbidities such as diabetes mellitus and dementia is known to be reduced by anti‐TNF‐α and anti‐IL‐1β therapy in patients with rheumatoid arthritis and comorbid type‐2 diabetes." (PMID 35971650, 2022). "For example, increased circHIPK3 stimulated the activation of the TLR4 pathway and NLRP3 inflammasome and the production of pro-inflammatory cytokines (e.g., TNF-α, IL-1β) in gouty arthritis whereas its silencing alleviated inflammatory damage in myocarditis and diabetes mellitus." (PMID 36072601, 2022). "We also determined the effect of BA and diabetes on inflammation in wound tissues, and the results showed that diabetes (STZ/VEH) treatment significantly increased mRNA levels of IL1β, IL6 and MCP1; treatment with BA-TOP and BA-IP partly, while BA-IP/TOP treatment completely, reversed this effect." (PMID 35415192, 2022). "It was shown that diabetes-induced activation of SCGs could produce various inflammatory factors, including IL-1β." (PMID 35529431, 2022). "Excess adipose tissues in obesity release nonesterified fatty acids (NEFAs), glycerol, adipokines, and pro-inflammatory cytokines (tumor necrosis factor-α) [TNF-α], interleukin [IL]-6, IL-1β), leading to insulin resistance (IR) and type 2 diabetes mellitus (T2DM)." (PMID 36157449, 2022). "One of the pro-inflammatory cytokines involved in diabetes is interleukin 1 beta (IL-1β)." (PMID 35513427, 2022). "The NLRP3 inflammasome and its products IL-1β and IL-18 may be potential targets for diabetes therapy." (PMID 36012516, 2022). "However, when we analyzed three M1 cytokines, IL-1β, IL-12, and IL-6, we found that diabetes microglia had significantly lower levels of IL-1β, significantly higher levels of IL-12 and unaltered levels of IL-6." (PMID 35935990, 2022). "Since we previously showed IL-1β mediates the development of systolic dysfunction and cardiac arrhythmias in diabetes mellitus and cardiorenal syndrome, and IL-1β remains elevated in Chagas disease patients, here we tested the role of IL-1β in CCC using a mouse model." (PMID 36341442, 2022). "We were not able to control for other comorbidities, which may have influenced cytokine levels (e.g., diabetes and IL-1β)." (PMID 35942057, 2022). "The expression of NLRP3/IL-1β/caspase-1 has been observed in patients with diabetes, myocardial infarction, arrhythmia, and cardiac hypertrophy, and some agents can improve the symptoms of cardiovascular disease in patients by inhibiting the occurrence of pyroptosis." (PMID 35647057, 2022).
diabetes (continued). "To study the role of IL-1β in wound healing in patients with diabetes, we collected serum and wound tissues from normal and diabetic individuals and performed ELISA/western blots to measure protein levels of IL-1β in the serum and tissues, respectively, and qPCR to measure IL-1β mRNA levels." (PMID 34054346, 2021). "In addition, persistent hyperglycemia due to diabetes induces IL-6- and IL-1β-mediated dysfunction of insulin secretion." (PMID 34836432, 2021). "Many studies have shown that the NLRP3 inflammasome can regulate IL-1β activation in diabetes." (PMID 33637069, 2021). "Serum levels of IL-1β are elevated in patients with diabetes." (PMID 34054346, 2021). "Diabetes occurs in part because the accumulation of activated innate immune cells in metabolic tissues leads to the release of inflammatory mediators, especially IL-1β and TNFα, which promote systemic insulin resistance and β-cell damage." (PMID 33936349, 2021). "Blockade of the effects of IL-1β is therefore a promising focus of study in diabetes therapeutics." (PMID 34054346, 2021). "It has been reported that IL-1β amplified systemic inflammation and impaired insulin signaling leading to insulin resistant and organ dysfunction in peripheral tissues and macrophages during type 2 diabetes mellitus." (PMID 33986669, 2021). "NLRP3 inflammasome-IL-1β secretion in cardiac macrophage induces a decrease in potassium current and an increase in calcium sparks in cardiomyocytes, promoting the development of diabetes-induced arrhythmia." (PMID 34512671, 2021). "Carvedilol is potent in decreasing IL-1β concentration or mRNA expression in the model of brain I/R injury, experimental myocardial infarction, drug-induced cardiotoxicity, diabetes, or even in the rat model of periodontitis." (PMID 34959638, 2021). "IL-1β contributes to increase the secretion of intercellular adhesion molecule-1, which is responsible for islet beta-cell injury and death, further exacerbating diabetes." (PMID 34938667, 2021). "In addition, in a rat diabetes model, exposure to Blautia was positively correlated with inflammatory indicators including, IL-1β, TNF-α, IL-6 and lipopolysaccharides." (PMID 34110438, 2021). "Diabetes-mediated retinal inflammation is one of the first detectable retinal pathologies in this murine model, wherein hyperglycemia induces multiple inflammatory processes, including IL-6, IL-1β, and VEGF production." (PMID 34456740, 2021). "Moreover, elevated levels of C-reactive protein (CRP), tumor necrosis factor-α (TNF-α), IL-6, IL-18, and IL-1β were reported among patients with type 2 diabetes mellitus displaying features of the insulin resistance syndrome." (PMID 34917685, 2021). "Diabetes (DM) is one of the chronic diseases that develop due to severe inflammation and manifests in an increase in pro-inflammatory cytokines and chemotaxis mediated by B and T lymphocytes, such as IL-1β and TNF-α, leading to insulin resistance." (PMID 35047540, 2021). "We chose to use 1 ng/ml IL-1β empirically, because this concentration promoted elevated expression of TNFα, IL-1β, IL-6 and IL-8 in hMC cultures like that observed in the vitreous of diabetic patients and retina of experimental diabetes models." (PMID 33958662, 2021). "This evidence supports a role of IL-1β in the pathogenesis of type 2 diabetes mellitus." (PMID 34638553, 2021). "Multiple icv injections of AZD7545 (6.4 nM of CSF concentration), GSK2837808A (2 μM of CSF concentration) or oxamate (25 μg) significantly attenuated the diabetes-induced expression of proinflammatory cytokines Tnf-α, Il-1β, and Il-6 mRNAs, in the hypothalamus." (PMID 33219201, 2020). "After treatment with metformin in diabetes-susceptible B4 cells, the expression of nutrition excess-induced innate immunity/inflammasome molecules was ameliorated, including MDA5, NLRP3, caspase-1, and IL-1β." (PMID 32849261, 2020).
diabetes (continued). "In order to determine the underlying mechanisms by which BAI-LZM inhibits renal fibrosis and decreases inflammation, the protein expression levels of NF-κB, p-NF-κB p65, IL-1β, IL-6 and mTOR in diabetic kidney tissues were assessed using IF, IHC and western blot analyses." (PMID 32398108, 2020). "Diabetes mellitus and AFB1 intoxication-induced oxidative stress in this study were associated with increased production of proinflammatory cytokines, IL-1β, IL-6, and TNF-α leading to hepatorenal injuries and the elevation of activities and levels of their function biomarkers." (PMID 32104544, 2020). "Prospective randomised clinical trials are needed to evaluate the effects of IL-6R inhibition on glycaemic indices, insulin sensitivity and pancreatic β cell function in patients with comorbid RA and diabetes and determine the clinical relevance of differences in IL-6R, IL-1β and TNF inhibition." (PMID 32907617, 2020). "Remarkably, ablation of astrocytic Pdk2 in the hypothalamus attenuated diabetes-induced local inflammation, characterized by increased levels of the inflammatory cytokines Tnf-α, Il-1β, and Il-6 mRNA, and proliferation and activation of GFAP-positive astrocytes and Iba-1-positive microglia." (PMID 33219201, 2020). "Remarkably, overexpression of hypothalamic PDK2 reversed the effects of Pdk2 KO on diabetes-induced Tnf-α, Il-1β, and Il-6 mRNA expression, food intake, blood glucose, and expression of Npy, Agrp, and Pomc in the diabetic hypothalamus at 3 weeks post-STZ injection." (PMID 33219201, 2020). "There was a significantly opposite trend in TNF-α, IL-1β, and IL-10 between the n-3 Adq-GDM group and n-3 Def-GDM group, which could lead to differential diabetes risk." (PMID 31340612, 2019). "In diabetes, we observed an increase in il-1β after metformin treatment (3 μM, 24 h) (p < 0.05)." (PMID 31197747, 2019). "We therefore not only, in this study, assessed HDAC3 mRNA, protein, and activity using brain hippocampus and cortex tissues, but also tested our hypothesis in cultured HBMEC under in vitro diabetes condition and hyperglycemia plus IL-1β exposure." (PMID 31101061, 2019). "IL-1β is a predominant cytokine in inflammatory conditions, especially in diabetic mellitus." (PMID 30937278, 2019). "This imbalance of IL-1β leads to pancreatic islet inflammation, aggravating diabetes mellitus." (PMID 30881587, 2019). "IL-1β is also a key contributor to the pathogenesis of diabetes." (PMID 31340612, 2019). "TNF-α and IL-1β were increased in the liver of GDM offspring, whereas IL-10, an anti-inflammatory cytokine, was decreased in GDM offspring, indicating an increased risk of developing diabetes." (PMID 31340612, 2019). "To assess whether CPT improves inflammatory responses in diabetes-induced hepatic inflammation, we assessed IL-6, IL-1β, and TNF-α amounts in serum." (PMID 31404259, 2019). "To examine whether pJNK1 inhibition could decrease diabetes-induced Kupffer cell activation, we analyzed the IL-1β expression in Kupffer cells in STZDM-JNK1-/- mice." (PMID 29851956, 2018). "In addition, our data confirmed that the pain behavior coincided with the expression changes of inflammatory cytokines (TNF-α, IL-1β, IL-6, and IL-10) in rats with diabetes induced by STZ." (PMID 29713362, 2018). "Inflammation from continuously increasing IL-1β and IL-18 in diabetes patients could also lead to retinal and kidney lesions." (PMID 30555415, 2018). "With regard to possible comorbidities that may influence IL-1β levels diabetes, myocarditis and other autoimmune diseases are among the most investigated ones." (PMID 28212578, 2017). "Thus we investigated the possible involvement of microglia in the inhibitory effect of clodronate liposomes on diabetes-induced Il1b expression, using murine microglial primary cell culture stimulated with AGE-BSA." (PMID 29170525, 2017).